HIF1A (hypoxia inducible factor 1 subunit alpha)
Diseases named in the same sentence as HIF1A in open-access papers (continued):
Sharing a sentence is not in itself a finding about the gene and the disease.
gastric cancer (continued). "The suppressive effects of HIF-1α on α5 integrin might allow gastric cancer cells to survive in vessels or the peritoneal cavity, resulting in distant metastasis and peritoneal dissemination." (PMID 24216696, 2013). "Furthermore, the contribution of HIF-1α to chemoresistance has been observed in several solid tumors, including gastric cancer." (PMID 22754381, 2012). "Subsequent studies should focus on whether diosgenin, when combined with shRNA of HIF-1α, is effectively applied to the animal gastric cancer model." (PMID 22754381, 2012). "The HIF-1α pathway is clearly involved in carcinogenesis of gastric cancer." (PMID 22479608, 2012). "Taken together, our results and the previous findings indicate that the upregulation of MMP-1 expression following the loss of HIF-1α might be an important step in the development of peritoneal dissemination from MKN45 and MKN74 gastric cancer cells." (PMID 23181099, 2012). "However, little is known concerning the mechanism and contributory roles of HIF-1α expression and the development of peritoneal dissemination in gastric cancer." (PMID 23181099, 2012). "Consistently, HIF-1α shRNA expression decreased the cell growth of gastric cancer cell lines." (PMID 21119667, 2011). "As the present study showed that IκBαM overexpression suppressed MVD in xenografted tumours derived from SNU-668 cells, we assessed whether HIF-1α mediates the effect of NF-κB activation in gastric cancer." (PMID 21119667, 2011). "Although HIF-1α was shown to increase angiogenesis and tumour growth of gastric cancer, the regulatory mechanism of HIF-1α activation in gastric cancer remains unclear." (PMID 21119667, 2011). "In conclusion, the results obtained from human gastric cancer specimens, gastric tumour xenografts, and cell culture experiments indicate that HIF-1α mediates NF-κB-induced angiogenesis by increasing VEGF expression and MVD, and that this occurs under hypoxic conditions." (PMID 21119667, 2011). "To obtain a better understanding of the mechanism involved in NF-κB-induced HIF-1α activation in gastric cancer cells, we investigated whether IκBαM stimulates HIF-1α degradation or inhibits its synthesis." (PMID 21119667, 2011). "Of these, HIF-1α and VEGF are recognized to be representative marker proteins of angiogenesis, and are known to be associated with pro-angiogenic phenotypes of numerous tumors, including gastric carcinoma." (PMID 21696576, 2011). "In addition, immunohistochemical tissue array analysis showed that HIF-1α was constitutively expressed in 27% of the 251 surgical samples of gastric carcinomas, and that this was positively correlated with NF-κB activation (P<0.001)." (PMID 21119667, 2011). "Functional inactivation of HIF-1α shifted the dose dependency of growth inhibition towards lower drug concentrations, suggesting that HIF-1α is capable to reduce chemotherapy susceptibility of gastric cancer cells under normoxic conditions." (PMID 20706634, 2010). "Inactivation of HIF-1α in gastric cancer cells resulted in robust elevation of chemosensitivity." (PMID 20706634, 2010). "However, due to the small number of patients who completed the follow-up (n=41), this investigation can solely describe a tendency of robust expression of HIF-1α in gastric cancer cells." (PMID 19223895, 2009). "This possibility is confirmed by observations that the mammalian target of rapamycin (mTOR), an upstream regulator of HIF, is activated in human gastric cancer, whereas attenuation of PI-3K/Akt/mTOR-mediated signalling by rapamycin effectively blocks HIF-1α in gastric cell lines." (PMID 19564950, 2009). "In addition, when the human gastric cancer cell line TMK-1 stably expressed a dominant negative form of HIF-1α, tumours grew slower, showed smaller overall vessel area and hampered vessel maturation when implanted orthotopically in nude mice." (PMID 19223895, 2009).
gastric cancer (continued). "Our characterisation of the temporospatial expression patterns of HIF-1α protein during the pathogenesis of human gastric adenocarcinoma are in line with earlier studies showing HIF-1α protein expression in the majority of human gastric cancer samples." (PMID 19223895, 2009). "Our results showed that, while HIF-1α was dispensable for cellular proliferation, functional and pharmacological inactivation of the factor lead to a significant reduction of migratory, invasive and adhesive features of human gastric cancer cells in vitro." (PMID 19223895, 2009). "Hence, we characterised for the first time the functional importance of HIF-1α for central cell biological properties of metastatic human gastric cancer cells." (PMID 19223895, 2009). "Furthermore, the HIF-1α-inhibitor 2-methoxy-estradiol significantly reduced metastatic properties of gastric cancer cells." (PMID 19223895, 2009). "The transcription factor HIF-1α (hypoxia-inducible factor 1α) is frequently overexpressed in human gastric cancer, and inhibition of HIF-1α has proven antitumour efficacy in rodent models, whereas the relevance of HIF-1α for the metastatic phenotype of gastric adenocarcinoma remains elusive." (PMID 19223895, 2009). "Hence, our data argue for a pivotal role of HIF-1α in the pathogenesis of later stages of human gastric cancer and its systemic spread." (PMID 19223895, 2009). "Therefore, we performed an array of in vitro experiments aimed at defining the importance of HIF-1α for local invasion and metastatic spread of gastric cancer cells." (PMID 19223895, 2009). "In the series of gastric cancer patients studied here, therefore, the beneficial effect of a focal pattern of HIF-1α expression on prognosis may relate to its proapoptotic and antiproliferative." (PMID 17179985, 2007). "Recently, HIF-1α has emerged as a key regulator in the growth of gastric cancer." (PMID 17166265, 2006). "This study reveals the core mechanism by which insulin-like growth factor 2 mRNA-binding protein 2 (IGF2BP2) drives tumor progression and radiotherapy resistance in gastric cancer (GC) through m6A-dependent regulation of hypoxia-inducible factor 1α (HIF1α)." (PMID 40469197, 2025). "Finally, we tested the effect of M2‐EX on HIF‐1α expression in gastric cancer cells." (PMID 38639382, 2024). "Accumulating evidence indicates that HIF-1α may be a potential driver of Hypoxia-induced HIF-1α/lncRNA-PMAN inhibits ferroptosis by promoting the cytoplasmic translocation of ELAVL1 in peritoneal dissemination from gastric cancer in gastric cancer." (PMID 39570876, 2024). "Therefore, agents that directly or indirectly inhibit HIF-1α signaling may become an effective strategy in gastric cancer treatment in the future." (PMID 36846589, 2023). "Finally, HIF1α promotes the proliferation of gastric cancer cells." (PMID 35956843, 2022). "Another study manifested that Quercetin could mediate the Akt-mTOR and hypoxia-induced factor 1 α (HIF-1α) signaling pathways to activate the autophagic process in gastric cancer cells and also restrict gastric cancer cell metastasis by blocking the uPA/uPAR function." (PMID 36471693, 2022). "Similarly, miR-224 was upregulated by hypoxia and HIF-1α in gastric cancer." (PMID 35006436, 2020). "Similarly, HIF-1α-induced activation of miR-224 targets Ras association domain family member 8 (RASSF8), stimulating NF-κB transcriptional activity and subcellular distribution to confer gastric cancer with more aggressive phenotypes." (PMID 32014012, 2020). "In addition, the lncRNA-mediated regulation of the mTOR/HIF-1α/P-gp signaling pathway marked by increased HIF-1a mRNA levels in gastric cancer cells might also suggest the alteration of HIF-1α transcriptional activity." (PMID 32014012, 2020).
gastric cancer (continued). "Whether HIF-1α mediates PKM2 expression in gastric carcinoma remains unclear." (PMID 33376737, 2020). "PFKFB2 expression is also enhanced in human gastric malignant tumors, being associated with increased levels of HIF-1α dependent genes, vascular endothelial growth factor (VEGF) and Glut1, indicating that HIF-1α could be responsible for the induction of PFKFB2 expression." (PMID 30234009, 2018). "However, prognostic and diagnostic values of HIF-1α for gastric cancer have not been systematically studied." (PMID 29899167, 2018). "Over-expressions of JMJD2C and HIF-1α in gastric cancer tissues were associated closely with the growth, invasion and metastasis of gastric tumor, implying that JMJD2C might be a bad prognosis marker for gastric cancer patients." (PMID 29207681, 2017). "We also showed the significance of regulation of HNF4α, as well as reduced HIF1α, in early gastric cancer (GC), as detected only by our PATHOME algorithm." (PMID 29050243, 2017). "In gastric cancer cells, PVT1 was demonstrated to upregulate HIF-1α expression by sponging miR-186 to revert miR-186-mediated repression of HIF-1α expression and consequentially promote GC cell progression indirectly." (PMID 28789687, 2017). "Therefore, we propose that NF-κB may enhance HIF-1α expression in gastric cancer cells under hypoxia, which needs further studies." (PMID 28173803, 2017). "Therefore, cancer therapy targeting HIF-1α may be effective in the hypoxic region within gastric cancer tissue." (PMID 26339797, 2015). "The current study identified that the inhibitory effect of KAI1 expression on the cell migration and invasion of gastric cancer was not mediated by HIF-1α, MMP-2 and MMP-9, but may be associated with the reduction in uPA and bFGF expression." (PMID 26622792, 2015). "Finally, using a tumor xenograft model, we proposed that HIF-1α inhibition combined with glucose plus insulin (GI) treatment may be a potential therapy for gastric cancer." (PMID 26339797, 2015). "In conclusion, our analyses show that the aberrant expression of HIF-1α, PTEN, CD44v6, and Survivin, as measured by IHC, may predict the 5-year overall survival risk and potential for invasion and metastasis in gastric cancer patients, particularly in Asian patients." (PMID 24647137, 2014). "As the incidence and mortality rate of gastric cancer are extremely higher in Eastern Asian especially China, Japan and Korea, we present a meta-analysis evaluating the prognostic impact of one subset of proteins in HIF-1α signaling in gastric cancer patients in subgroup of different continents." (PMID 24647137, 2014). "In the future, the important role of HIF-1α in radioresistance might be revealed in gastric cancer." (PMID 24216696, 2013). "To demonstrate our hypothesis, we analyzed the expression of hypoxia inducible factor-1α (HIF-1α) and Foxp3 in gastric cancer tissues, assessed the effect of hypoxia on TGF-β1 production in cancer cell lines, and finally elucidated the role of hypoxia mediating Treg enrichment in gastric cancer." (PMID 23723999, 2013). "Therefore, HIF-1α expression might be suppressed during the development of peritoneal dissemination from primary gastric cancer." (PMID 23181099, 2012). "Thus, HIF-1α and NF-κB may be candidate molecular targets for gastric cancer therapy, and in particular, blocking the NF-κB/HIF-1α pathway with appropriate inhibitors might be useful therapeutically for treating gastric carcinoma." (PMID 21119667, 2011). "Of note, HIF-1α-deficient AGS KD cells overexpressing p65 were considerable more resistant to 5-FU treatment compared to AGS KD cells transfected with the control vector, consistent with an essential role of NF-κB in mediating chemoresistance towards 5-FU in gastric cancer cells." (PMID 20706634, 2010).
gastric cancer (continued). "Intriguingly, the integrative predictive model hinging upon the genetic signatures of JUN, HIF1A, and PTGS2 emerges as a robust prognostic indicator correlating with poorer clinical outcomes in gastric cancer patients." (PMID 40391580, 2025). "The interaction between TET1 and HIF-1A positively regulates PD-L1, and the overexpression of PD-L1 enhances the function of the NUTM2A-AS1/miR-376a axis in treating malignant tumors in gastric cancer." (PMID 40861273, 2025). "We found it particularly interesting that in stomach cancer cells, ATAD2 is upregulated during hypoxia in a Hif1α-dependent manner and promotes cell proliferation." (PMID 40962957, 2025). "RNA pull-down assay demonstrated that IGF2BP2 was significantly enriched in MKN74 gastric cancer cells and predominantly bound to the CDS region of HIF1α mRNA." (PMID 40469197, 2025). "For example, under hypoxic microenvironments, HIF-1α acts on NAT10 HRE sequences, activating its expression and promoting glucose metabolic reprogramming in gastric cancer cells." (PMID 41298345, 2025). "Previous studies have reported that N4-acetylcytidine drives glycolysis in gastric cancer via a NAT10/SEPT9/HIF-1α positive feedback loop, and the lncRNA CCAT1 facilitates the progression of gastric cancer via PTBP1-mediated enhancement of glycolysis." (PMID 40796546, 2025). "Suppressed HIF‐1α ubiquitination and degradation by DDR1 was reported to be involved in the malignant progression of gastric cancer." (PMID 40515512, 2025). "In gastric endothelial cells, BGN enhances NF-κB binding to the HIF-1α promoter via TLR2 and TLR4 signaling, resulting in increased VEGF expression and enhanced migration of gastric cancer cells." (PMID 41465449, 2025). "Mechanistically, OPN can bind to the αvβ3 integrin protein of gastric cancer cells, activate the PI3K/Akt signaling pathway, and then upregulate the expression of HIF-1α." (PMID 40563539, 2025). "In gastric cancer, NUTM2A-AS1 sponges miR-376a, which normally suppresses TET1 and HIF-1A; the resulting increase in these proteins subsequently elevates PD-L1 expression, thereby promoting cell viability, invasion, and chemoresistance." (PMID 40903777, 2025). "Key findings reveal that in gastric cancer, NUTM2A-AS1 functions as a ceRNA for miR‐376a, leading to upregulation of TET1 and HIF-1A and subsequent increase in PD-L1 expression, while also modulating matrine resistance via the miR‐613/ROS/VEGFA axis." (PMID 40903777, 2025). "In the realm of clinical translation, we leveraged the genetic signatures of JUN, HIF1A, and PTGS2 to establish a predictive model tailored for gastric cancer prognosis." (PMID 40391580, 2025). "In a particular study, hypoxia was identified as a factor influencing the NF-κB-mediated regulation of HIF-1α and VEGF expression in gastric cancer cells." (PMID 39370481, 2025). "In gastric cancer, by indirectly enhancing PD-L1 expression through the miR-376a/TET1/HIF-1A pathway, NUTM2A-AS1 promotes immune escape and chemoresistance." (PMID 40903777, 2025). "For instance, NPRA (Natriuretic peptide receptor A) interacts with HIF-1α, preventing its proteolysis and increasing VEGF expression to enhance angiogenesis in gastric cancer." (PMID 40630134, 2025). "This HIF1-α/HYPAL/miR-431-5p/CDK14 axis activates the Wnt-β-catenin pathway, promoting gastric cancer cell proliferation and inhibiting apoptosis." (PMID 39940704, 2025). "Because HIF-1α is an upstream regulatory factor of VEGF, the reduced activity of the HIF-1α/VEGF signaling pathway indicates a better prognosis for gastric cancer patients." (PMID 40563539, 2025). "The HIF-1α/HYPAL/miR-431-5p/CDK14 axis activates the Wnt/β-catenin signaling pathway, thereby inducing proliferation in gastric cancer cells while inhibiting apoptosis." (PMID 40861273, 2025).
gastric cancer (continued). "As observed in ameloblastoma and gastric cancer cells, under hypoxia, TGF-β is upregulated due to HIF-1α-mediated gene expression, intensifying signal transduction through the TGF-β/Smad pathway." (PMID 40710312, 2025). "First, HMGB2 boosts the transcriptional activity of HIF-1α, leading to upregulation of glycolytic enzymes such as LDHA, PKM2, and HK2, which help gastric cancer cells sustain glycolysis under hypoxic conditions." (PMID 41220952, 2025). "Hypoxic conditions increase NRF2, HIF-1α, and HO-1 expression in gastric cancer cells, whereas NRF2 inhibition suppresses cancer invasion via concomitant reductions in HIF-1α expression." (PMID 38424190, 2024). "Specifically, HIF-1α interacts with hormone response elements (HREs) within the promoter region of lncRNA BC005927, inducing the oncogenic role of lncRNA BC005927 in gastric cancer through the upregulation of the EPH receptor B4 (EPHB4)." (PMID 38339408, 2024). "We then used the inhibitors for β‐catenin and HIF‐1α signaling pathways to determine the importance of δ‐catenin and HIF‐1α regulation by M2‐EX in promoting glycolysis and gastric cancer progression." (PMID 38639382, 2024). "NAT10 receives regulation of a critical transcription factor HIF‐1α in the hypoxia response, which triggers the activation of the HIF‐1 pathway and regulates ac4C to enhance hypoxia tolerance in gastric cancer cells." (PMID 39006762, 2024). "In gastric cancer tissues and cell lines, a low expression of SIRT6 leads to the upregulation of HIF-1α and the activation of various AEG enzymes, thereby promoting gastric cancer cell growth." (PMID 39906672, 2024). "Further research has identified that dextran sulfate targets HIF-1α, inhibiting EMT in gastric cancer cells at both mRNA and protein levels, suggesting that HIF-1α and dextran sulfate hold promise for gastric cancer immunotherapy." (PMID 39840050, 2024). "By modulating the activity of HIF-1α and c-Myc, STAT3 significantly enhances AEG and proliferation in gastric cancer cells, underscoring its pivotal role in the SIRT6-regulated AEG pathway." (PMID 39906672, 2024). "Previous studies have shown that gastric cancer increases Treg levels through the TGF-β signaling pathway under hypoxic conditions, and high expression of hypoxia-inducible factor-1α (HIF-1α) promotes EMT." (PMID 39840050, 2024). "Similarly, peritoneal metastases of gastric cancer (GC), which are inherently characterized by hypoxia, leverage the HIF-1α pathway to counteract ferroptosis." (PMID 38217037, 2024). "In gastric cancer cells, SHMT2 modulates the stability of HIF1α, thus controlling a network of hypoxia-responsive genes that have regulatory effects on complementary pathways, including VEGF and STAT3." (PMID 39309860, 2024). "In tissue specimens from patients with gastric cancer, high NRF2 expression levels were positively correlated with HIF-1α and HO-1 expression." (PMID 38424190, 2024). "PPI analysis revealed five important proteins, such as ALB, BCL-2, NF-κB, HIF1A, and IL6, from 44 target proteins of gastric cancer according to statistical significance." (PMID 39816318, 2024). "We found that in the presence of β‐catenin inhibitor ICG001 and HIF‐1α inhibitor PX‐478, the upregulation of glycolysis‐related genes PKM2, GLUTA, HK2, and LDHA in gastric cancer cells by M2‐EX was greatly attenuated." (PMID 38639382, 2024). "Nevertheless, further studies are needed to uncover the mechanisms for this context-dependent and subcellular compartment-dependent regulation of CD133, the influence that CD133 brings upon gastric cancer cells, and the regulation of CD133 by HIF-1α." (PMID 36846589, 2023). "Knocking down HIF-1α reverted these changes, showing the involvement of HIF-1α in the proliferation of gastric cancer stem cells and maintenance of stemness." (PMID 36846589, 2023).